INS (insulin)
Diseases named in the same sentence as INS in open-access papers (continued):
Sharing a sentence is not in itself a finding about the gene and the disease.
cognitive disorder (25 papers, 2013 to 2025). A disease affects cognitive processes. "Our findings revealed that binding insulin with these nanofibers offered a feasible strategy to address the rising prevalence of cognitive diseases in both insulin-deficient T1D and, possibly, insulin-resistant T2D patients." (PMID 35056977, 2021). "Impaired insulin signaling has been implicated in AD, thus underscoring a shared dysregulated pathway between a cognitive disease and a metabolic disorder." (PMID 23915208, 2013).
non-small cell lung carcinoma (25 papers, 2011 to 2025). A group of at least three distinct histological types of lung cancer, including non-small cell squamous cell carcinoma, adenocarcinoma, and large cell carcinoma. "The top 20 pathways were primarily “Small cell lung cancer”, “Non-small cell lung cancer”, “Hedgehog signaling pathway”, and “Insulin resistance”." (PMID 41444284, 2025). "Some studies have found that metformin may improve chemotherapy outcomes for patients with non-small cell lung carcinoma compared with other therapies (e.g., insulin, sulfonylureas)." (PMID 37478113, 2023). "Insulin and insulin-like growth factor receptor (IGFR)-mediated molecular pathways are important effectors of neoplastic transformation in non-small cell lung cancer and squamous cell carcinoma of the head and neck." (PMID 25096247, 2014).
pheochromocytoma (25 papers, 2011 to 2026). "Impaired insulin secretion is the principal cause of hyperglycemia in secretory PPGLs and has been recognized from early case series of patients with pheochromocytomas." (PMID 37731140, 2023). "Impaired secretion of insulin by catecholamines on phaeochromocytoma is caused mainly through adrenergic α2 receptors of β-cells in pancreatic islets." (PMID 33324347, 2020). "This makes it unlikely that GLP-1R stimulation could cause the release of clinically significant amounts of insulin from a phaeochromocytoma." (PMID 41488993, 2026). "Dysregulated ectopic production of insulin and related molecules could cause or contribute to the two kinds of glucose imbalances seen in patients with phaeochromocytoma." (PMID 34170845, 2021). "On the other hand, increased insulin resistance on phaeochromocytoma is caused by stimulated gluconeogenesis and glycogenolysis in the liver, which arises from an excess of glucagon and increase of free fatty acids as well as elevated glucose uptake in skeletal muscle." (PMID 33324347, 2020). "However, one cannot exclude that clonal expansion of cells containing both proteins could occur very rarely, greatly increasing the number of such cells, and cause GLP-1R-stimulated insulin release and hypoglycaemic episodes in phaeochromocytoma patients." (PMID 41488993, 2026). "The number and proportion of phaeochromocytoma cells that contain insulin or GLP-1R were scored in all six tumours together and for each tumour separately." (PMID 41488993, 2026). "Among those are insulin produced in some tumour cells in most phaeochromocytomas and GLP-1R found in some phaeochromocytomas." (PMID 41488993, 2026). "Most phaeochromocytomas contain tumour cells producing insulin, and about half of phaeochromocytomas contain tumour cells producing GLP-1R." (PMID 41488993, 2026). "In the future, for phaeochromocytoma patients with hypoglycaemic attacks, it would be important to study insulin release before and after the removal of the tumour and perform detailed studies of the tumour." (PMID 41488993, 2026). "Most phaeochromocytomas produce insulin, and some produce glucagon-like peptide 1 receptor (GLP-1R)." (PMID 41488993, 2026). "Most phaeochromocytomas show ectopic production of insulin, insulin transcript and a related hybrid transcript." (PMID 41488993, 2026). "In line with this notion, a recent prospective study in patients with pheochromocytomas with adrenergic phenotype, demonstrates impaired first phase of insulin secretion and GLP-1 secretion." (PMID 37731140, 2023). "In fact, euglycemic hyper-insulinemic clamping performed before and after surgery in patients with pheochromocytoma demonstrated that endogenous catecholamine excess induces insulin insensitivity even in patients with normal glucose tolerance." (PMID 37822367, 2023). "INS expression was detected in pancreatic adenocarcinoma and rare neural tumours, pheochromocytoma and paraganglioma, and in their and glioblastoma and thymoma’s corresponding normal samples." (PMID 34554347, 2022). "Neuronal transformation is observed in many neuroendocrine cells in vitro, including carcinoid tumors, small cell carcinoma of the lung, pheochromocytoma and insulin-producing pancreatic islet cell tumors." (PMID 35370935, 2022). "Normal β-cells constitute only about 2% of pancreatic cells so a phaeochromocytoma of around 5 cm would contain a sufficient number of insulin-producing cells." (PMID 34170845, 2021). "His glucose levels were incredibly difficult to manage with an insulin infusion until the pheochromocytoma was resected and then required aggressive glucose supplementation." (PMID 34583724, 2021). "Several lines of evidence further support the possibility of insulin expression in phaeochromocytomas." (PMID 34170845, 2021). "In this study, we report that most phaeochromocytomas overexpress INS and INS-IGF2 transcripts and insulin." (PMID 34170845, 2021).
pheochromocytoma (continued). "In patients with phaeochromocytoma, Wilber and co-workers reported that insulin secretion was inhibited by an excess of catecholamine." (PMID 33324347, 2020). "They noted that improved insulin secretion after surgical removal of phaeochromocytoma/paraganglioma with hyperglycemic clamps as well as an oral glucose tolerance test." (PMID 33324347, 2020). "Much of the data relating to pheochromocytoma, paraganglioma, and altered glucose and insulin homeostasis remain anecdotal." (PMID 31275775, 2019). "Of the 20 phaeochromocytomas, 15 show tumour cells producing insulin." (PMID 41488993, 2026). "Most phaeochromocytomas contain tumour cells producing insulin." (PMID 41488993, 2026). "Altogether with another study used insulin treatment in a cloned rat pheochromocytoma cell lines showed that increase in the p-GSK-3β (Ser9) levels agreed roughly with the repression in p-GSK-3β (Tyr216) because insulin activate Akt, an inhibitor for ERK1/2 as well as GSK-3β (Tyr216)." (PMID 40381124, 2025). "Staining with anti-insulin was described in five of seven phaeochromocytomas." (PMID 34170845, 2021). "In conclusion, activation of expression from the insulin locus is common in phaeochromocytomas." (PMID 34170845, 2021). "The activation of a wider region around the insulin gene may have possible autocrine stimulatory growth effects in phaeochromocytomas." (PMID 34170845, 2021). "It has been observed that endocrine neoplasias, such as pheochromocytoma, medullary thyroid carcinoma, carcinoid, insulin-producing pancreatic tumor, and small cell lung carcinoma (SCLC) may differentiate into neural cells in vitro." (PMID 33001343, 2021). "It has been postulated that catecholamine induced β-adrenoceptor- mediated release of insulin from pancreatic β-cells may override the prevailing α-adrenoceptor mediated inhibition of release and the insulin resistance seen in most phaeochromocytoma patients." (PMID 34170845, 2021). "The few cases that reported reactive hypoglycaemia in phaeochromocytoma suggest that these tumours may have a trigger for insulin secretion." (PMID 34170845, 2021). "Clinical studies revealed patients with phaeochromocytoma had impaired insulin secretion." (PMID 33324347, 2020). "The findings indicated that patients with phaeochromocytoma could have both impaired insulin secretion and increased insulin resistance by an excess of catecholamine." (PMID 33324347, 2020). "Clinicians may be faced with life-threatening disturbances in glucose and insulin homeostasis when managing pheochromocytomas and/or paragangliomas." (PMID 31275775, 2019). "While IGF-II has been implicated in non-insulin mediated hypoglycemia in many tumors, no reports to date indicate this mechanism operates in pheochromocytomas and paragangliomas." (PMID 31275775, 2019). "Interestingly, recently published data reveal that 95% of pheochromocytomas express insulin transcript and the hybrid insulin-IGF-2 transcript and that 80% stain positive with anti-insulin antibodies, suggesting that the transcripts are translated to polypeptides." (PMID 37731140, 2023). "What could give phaeochromocytoma cells the ability to express insulin?" (PMID 34170845, 2021). "Thus, there are several possible mechanisms by which genomic changes activating transcription from the IGF2 gene also could increase the expression of the INS gene in phaeochromocytoma." (PMID 34170845, 2021). "Therefore, if a phaeochromocytoma produces much insulin, from the whole tumour or a local clone, and the normal regulatory brake on secretion of insulin to the blood is defect, the tumour could cause hypoglycaemia." (PMID 34170845, 2021). "These molecular findings indicated an excess of catecholamine in phaeochromocytoma could lead to both impaired insulin secretion and increased insulin resistance through various adrenergic receptors as well as different actions between epinephrine and norepinephrine in them." (PMID 33324347, 2020).
pheochromocytoma (continued). "Komada and co-workers demonstrated impairment of insulin secretion, particularly in an early phase of the insulin secretory response in 13 patients with phaeochromocytoma/paraganglioma (extra-adrenal phaeochromocytoma) (11 with phaeochromocytoma and two with paraganglioma)." (PMID 33324347, 2020). "Thus, phaeochromocytomas may cause hypoglycaemia from insulin release also without stimulation of the GLP-1R." (PMID 41488993, 2026). "In 20 phaeochromocytomas, we performed sequential double staining with anti-insulin and anti-GLP-1R antibodies and, in selected cases, staining with anti-insulin alone." (PMID 41488993, 2026). "The expression of INS and INS-IGF2 transcriptswas also analysed in 182 phaeochromocytomas and paragangliomas using publicly available datasets in The Cancer Genome Atlas (TCGA) Database." (PMID 34170845, 2021). "While many manifestations of pheochromocytoma in the setting of catecholamine excess are well described, the varied manifestations of disturbed glucose and insulin metabolism are not as well-recognized." (PMID 31275775, 2019). "Moreover, resistin, an insulin-antagonizing adipokine, is shown to be higher in patients with pheochromocytoma and DM than in non-diabetic ones, with its level being decreased post-surgery." (PMID 37731140, 2023). "In patients with pheochromocytoma and glucagonoma, pioglitazone could be used as the third-line therapy, and when glycaemic control is not obtained, insulin therapy should be started." (PMID 37842314, 2023). "GLP1R expression/protein has been found on phaeochromocytoma cells and tumours, but whether they function normally or if they are expressed on cells positive for anti-insulin staining is not known." (PMID 34170845, 2021). "Therefore, we tested whether insulin transcript (INS), insulin, and a hybrid read-through transcript between exons from insulin and insulin-like growth factor 2 (INS-IGF2) were expressed in phaeochromocytomas." (PMID 34170845, 2021). "Increased serum metanephrines in an asymptomatic pheochromocytoma may impact glucose and insulin parameters without raising blood pressure, as suggested by Uehara." (PMID 31275775, 2019). "Normal adrenal medulla, where phaeochromocytomas originate, also does not stain for GLP-1R or insulin." (PMID 41488993, 2026).
renal fibrosis (25 papers, 2013 to 2026). A final common manifestation of a wide variety of chronic kidney diseases characterized by glomerulosclerosis and tubulointerstitial fibrosis. "Baicalin therapy boosted insulin production and ameliorated renal fibrosis via activating the IGF-1/IGF-1R/p38 signaling pathway." (PMID 39911847, 2025). "The results of our study showed that renal fibrosis was improved significantly after islet transplantation compared with that observed after insulin therapy." (PMID 27725943, 2016). "However, insulin treatment significantly attenuated renal fibrosis, as quantified by Masson’s trichrome staining (p < 0.05)." (PMID 41601953, 2026). "Notably, butyrate has been demonstrated to improve insulin sensitivity and alleviate renal fibrosis and inflammatory responses by inhibiting HDACs." (PMID 41048436, 2025). "In essence, the dysregulation of gut microbiota triggers a complex cascade of adverse effects, including compromised intestinal epithelial barrier integrity, increased inflammation, oxidative stress, reduced insulin sensitivity, renal fibrosis, and the progressive development of DN." (PMID 39845884, 2024). "Insulin may induce renal fibrosis by stimulating mesangial cells and proximal tubule cells to produce tumor growth factor β (TGF-β)." (PMID 23690758, 2013). "Male Tgfb3+/− mice at 4 months of age exhibit renal fibrosis, EMT and glomerular damage with foot process effacement in podocytes, and show albuminuria, loss of renal function, lipid accumulation, lipid metabolism deregulation, insulin resistance and mitochondrial dysfunction with oxidative stress." (PMID 34431499, 2021). "In conclusion, our results demonstrated that islet transplantation could reverse various symptoms of early DN in a rat model, and the ameliorative effects on kidney injury and renal fibrosis were obviously better with islet transplantation than with insulin therapy." (PMID 27725943, 2016). "In 2022, a study found that NAC combined with insulin administration upregulated the level of SLC7A11 mRNA in the kidney and increased the intracellular GSH concentration by nearly 4 times, thereby reducing renal fibrosis and improving renal function." (PMID 39872050, 2024). "After combined treatment with insulin and UA, the expression level of TGF-β1 was reduced, suggesting that UA may improve the extent of renal fibrosis by reducing TGF-β1 expression." (PMID 36249783, 2022). "It was reported that PDIA3 was highly induced in neurodegenerative disease like prion disease, renal fibrosis, obese insulin-resistant nondiabetic individuals and livers of rats fed high-fat diet." (PMID 26214517, 2015). "This was accompanied by increased levels of insulin production with baicalin treatment, suggesting that baicalin may modulate the activation of the IGF-1/IGF-1R/p38 signalling pathway ameliorating STZ-induced renal fibrosis in DN rats." (PMID 39911847, 2025). "However, hyperglycaemic control with insulin did not improve the progression of renal fibrosis and the activation of TGF-β1 and Shh signalling." (PMID 29196746, 2017). "However, treatment of insulin to diabetic mice did not affect the tubular injury and renal fibrosis induced by IRI." (PMID 29196746, 2017). "However, treatment of insulin did not improved renal fibrosis in our animal model showing progressive kidney fibrosis after IRI, even though insulin showed significantly improved control of blood glucose level." (PMID 29196746, 2017). "In contrast, with insulin treatment, the blood glucose level, ACR, and protein-to-creatinine ratio were not well controlled, and the expression of related renal fibrosis factors was obviously higher than that observed following islet transplantation in this study." (PMID 27725943, 2016).
arteriosclerosis (24 papers, 2010 to 2025). A vascular disorder characterized by thickening and hardening of the walls of the arteries. "In the basic model (Model 1), sex, smoking, BMI, fasting insulin, and HbA1c associated with the incidence of arteriosclerosis." (PMID 34746266, 2021). "Fasting insulin change itself associated with arteriosclerosis." (PMID 34746266, 2021). "Abnormal insulin signaling in endothelial cells (ECs), vascular smooth muscle cells (VSMCs), and macrophages accelerates the formation and development of arteriosclerosis." (PMID 40144296, 2025). "It is pivotal in enhancing insulin sensitivity, warding off arteriosclerosis, and reducing inflammation." (PMID 39337923, 2024). "Adiponectin, which is one of the adipokines, has a variety of physiological activities that are beneficial to the body, such as restoring insulin to normal and preventing arteriosclerosis and cardiovascular diseases." (PMID 37571282, 2023). "An increase in insulin over time and being hyperinsulinemic enhanced the risk of developing increased IMT and arteriosclerosis." (PMID 34746266, 2021). "Meanwhile, arteriosclerosis led to decreased blood perfusion in the pancreas, resulting in impaired pancreatic function, resulting in decreased insulin secretion levels and increased blood glucose." (PMID 34899903, 2021). "Baseline characteristics and changes of BMI and/or fasting insulin during follow-up as risk factors of increased IMT and arteriosclerosis." (PMID 34746266, 2021). "On the other hand, adiponectin helps to repair damaged blood vessel walls, prevent arteriosclerosis, increase insulin’s action and lower blood pressure." (PMID 32397568, 2020). "At the same time, the lack of insulin causes an increase in the production of ROS (reactive oxygen species) and chronic inflammation that consequently accelerates the development of arteriosclerosis and cardiovascular disease." (PMID 37432258, 2023). "Smoking provided a slightly higher relative and adjusted relative risk for increased IMT (ARR: 2.3 [1.5, 3.7]) than fasting insulin and was not stronger associated than fasting insulin as risk factor for arteriosclerosis (ARR: 2.3 [1.3, 3.6])." (PMID 34746266, 2021). "Moreover, comprehensive modeling revealed that in addition insulin changes over time have a significant association with the incidence of increased IMT and arteriosclerosis." (PMID 34746266, 2021). "However, based on the present results, especially when considering changes of fasting insulin and BMI over time, higher fasting insulin levels exhibit a stronger association with increased IMT and arteriosclerosis than BMI." (PMID 34746266, 2021). "Low skeletal muscle mass may impair glucose homeostasis, reduce insulin sensitivity, and lead to IR, which can increase the blood pressure and blood lipid levels through a series of reactions and contribute to the process of arteriosclerosis." (PMID 34746254, 2021). "The addition of fasting insulin to the risk factors age {for increased IMT (ARR: 2.2 [1.4, 3.6])} or sex {for arteriosclerosis (ARR: 2.8 [1.9, 4.0])} yielded higher relative risks than the addition of BMI with regard to increased IMT (ARR: 1.8 [1.2, 2.8]) or arteriosclerosis (ARR: 2.0 [1.4, 2.8])." (PMID 34746266, 2021). "Interestingly, including the parameter smoking did not lead to a higher risk for increased IMT or arteriosclerosis than conferred by high fasting insulin levels." (PMID 34746266, 2021). "Fasting insulin change during follow-up but not BMI change associated with increased IMT and arteriosclerosis (both p < 0.001)." (PMID 34746266, 2021). "This interrelation supports the assumption that higher fasting insulin levels or a hyperinsulinemic status rather than elevated fasting blood glucose levels mediate the development of arteriosclerosis." (PMID 34746266, 2021).